MEG3 (maternally expressed 3)
Diseases named in the same sentence as MEG3 in open-access papers (continued):
Sharing a sentence is not in itself a finding about the gene and the disease.
myocardial infarction (10 papers, 2016 to 2024). Gross necrosis of the myocardium, as a result of interruption of the blood supply to the area, as in coronary thrombosis. "In addition to protein-coding genes, three long non-coding RNA genes were also differentially edited, including myocardial infarction-associated transcript (Miat), small nucleolar RNA host gene 11 (Snhg11) and maternally expressed gene 3 (Meg3)." (PMID 39135964, 2024). "In addition, recent studies have identified a role for Meg3, autophagy promoting factor (Apf), and myocardial infarction-associated transcript (MIRT) in myocardial infarction." (PMID 37034355, 2023). "To identify the potential effect of lncRNA MEG3 during myocardial infarction (MI), we measured its expression levels in infarct hearts and hypoxic neonatal mice ventricular myocytes (NMVMs) by quantitative real‐time PCR (qRT‐PCR)." (PMID 31631486, 2019). "Besides, knockdown of MEG3 or EGCG treatment demonstrated a pronounced capacity to impede myocardial infarction size, mitigate myocardial structural alterations, and mitigate cellular apoptosis within the MI models." (PMID 38057891, 2023). "Given that hypoxia inhibits CPC viability and proliferation through modulating MEG3 expression, inhibition of the MEG3/miR22 pathway might be a potential mechanism and target for the development of effective drugs for myocardial repair following myocardial infarction." (PMID 33922114, 2021).
Temple syndrome (10 papers, 2018 to 2024). "Temple Syndrome (TS14) in humans is associated with aberrant biallelic expression of the MEG3 ncRNA polycistron at the DLK1-DIO3 domain." (PMID 37686455, 2023). "Epimutations and microdeletions that affect the paternally methylated ICR, or the promoter of the MEG3 polycistron, are causally involved in two congenital imprinting disorders: Temple Syndrome (TS14, OMIM 616222) and Kagami-Ogata Syndrome (KOS14, OMIM 608149)." (PMID 37686455, 2023). "According to a different study, the Dlk1/Meg3 region is hypomethylated in children with temple syndrome, a condition marked by pre- and postnatal growth retardation, feeding difficulties, and motor development delay." (PMID 39543691, 2024). "A single study in patients with Temple syndrome has shown that DNA-methylation of the MEG3- and MEG8- differentially methylated region depends on the DNA-methylation pattern of the IG-differentially methylated region." (PMID 36114498, 2022). "Since ZNF445 binds to the MEG3/DLK1:IG-DMR and other iDMRs affected in this patient, the development of Temple syndrome and MLID would primarily be explained by the ZNF445 variant." (PMID 34039421, 2021). "Temple Syndrome (TS14) is a human imprinting disorder (ID) characterized by increased expression of the ncRNA polycistron, affecting MEG3, MEG8 (called Rian in the mouse) and MIRG RNA levels." (PMID 38613389, 2024). "In humans, epimutations and microdeletions that affect the IG-DMR or the MEG3 promoter are observed in two congenital imprinting disorders (IDs), Kagami-Ogata Syndrome (KOS14, OMIM 608149) and Temple Syndrome (TS14, OMIM 616222)." (PMID 38613389, 2024). "In mice, ZFP57 plays the predominant role in the maintenance of imprinting, whereas, in its absence, ZFP445 is required to preserve methylation in a subset of imprinting control regions such as those present in the MEG3/DLK1:IG-DMR, that involved in Temples’ syndrome." (PMID 38909248, 2024). "Particularly, we predict that in patients with Temple Syndrome (TS14), and in some patients with the clinically overlapping Silver-Russell Syndrome (SRS), their aberrant, biallelic MEG3 expression would lead to strongly reduced DLK1 in tissues in which this non-canonical Notch ligand is imprinted." (PMID 38613389, 2024). "Likewise, there was not any synergic effect for growth failure in SRS1 who had additional LoM of MEG3:TSS-DMR in 14q32.2, which is molecularly corresponding to Temple syndrome (OMIM #616222)." (PMID 37594968, 2023).
cardiac hypertrophy (9 papers, 2016 to 2023). "A number of lncRNAs, such as maternally expressed 3 (Meg3), myosin heavy-chain-associated RNA transcripts (Mhrt), cardiac hypertrophy-related factor (Chrf), Myocardial Infarction–Associated Transcript (Miat) have been reported to be involved in cardiac hypertrophy." (PMID 33732733, 2021). "Similar to CHRF, overexpression of the LncRNA MEG3 (Maternally expressed gene 3) also leads to myocardial hypertrophy." (PMID 37762106, 2023). "Upon MEG3 silencing, pathologic features such as myocardial hypertrophy, fibrosis, and diastolic dysfunction were relieved after 6 weeks in a mouse model of arterial spasm coarctation of the aorta." (PMID 37762106, 2023). "They found that MEG3 contributes to the pathogenesis of cardiac hypertrophy by competing with miR-361-5p binding and, consequently, upregulating HDAC9 expression." (PMID 34318404, 2021). "All our findings revealed that STAT3-inducetd upregulation of lncRNA MEG3 controls cardiac hypertrophy by regulating miR-362-5p/HDAC9 axis." (PMID 30679521, 2019). "Afterwards, the molecular mechanism by which MEG3 exert its functions in cardiac hypertrophy was investigated." (PMID 30679521, 2019). "Accordingly, we confirmed that MEG3 acts as a ceRNA by competitively binding with miR-361-5p in cardiac hypertrophy." (PMID 30679521, 2019). "In the process of cardiac hypertrophy, the role of lncRNA MEG3 cannot be ignored." (PMID 36523500, 2022). "MEG3 may, therefore, function as a positive regulator in the setting of cardiac hypertrophy via its interaction with the miR-361-5p/HDAC9 axis." (PMID 34318404, 2021). "Here, we found that MEG3 contributed to the pathogenesis of cardiac hypertrophy." (PMID 30679521, 2019). "Therefore, this study aims to investigate the specific role of MEG3 in the progression of cardiac hypertrophy." (PMID 30679521, 2019). "Whereas, it is unknown whether MEG3 regulates the growth of cardiac hypertrophy." (PMID 30679521, 2019). "Mechanically, MEG3 could affect cardiac hypertrophy by regulating gene expression." (PMID 30679521, 2019). "In this study, we hypothesized that MEG3 exert function of ceRNA in cardiac hypertrophy." (PMID 30679521, 2019). "In addition to validating known EZH2-binding ncRNAs (e.g., Gas5, Meg3, and Malat1), our findings reveal a large panel of novel ncRNAs involved in the dynamic regulation of the EZH2 function during AngII-induced cardiac hypertrophy." (PMID 33732733, 2021). "Furthermore, MEG3 can act as a ceRNA to regulate miR-361-5p and HDAC9 in cardiac hypertrophy." (PMID 30679521, 2019). "Activated by STAT3, MEG3 competitively binds and inhibits miR-361-5p, upregulates downstream HDAC9 protein, and has a negative effect on cardiac hypertrophy." (PMID 36523500, 2022).
diabetic nephropathy (9 papers, 2019 to 2026). "Strikingly, lncRNA MEG3 inactivated the Wnt/β-catenin pathway and reduced podocyte injury in diabetic nephropathy." (PMID 36313695, 2022). "However, MEG3 may play a pro-fibrosis role because it has been demonstrated to enhance fibrosis and inflammatory responses in diabetic nephropathy through the miR-181a/Egr1/TLR4 axis." (PMID 35890132, 2022). "Moreover, lncRNA MEG3 sponged miR-145 and impacted the development of diabetic nephropathy." (PMID 36313695, 2022). "LncRNA MEG3 increased fibrosis and inflammation through regulating miR-181a, Egr-1 and TLR4 in diabetic nephropathy." (PMID 36313695, 2022). "MEG3 facilitated inflammatory response and fibrosis by regulating the miR-181a/Egr-1/TLR4 axis in diabetic nephropathy." (PMID 34672863, 2021). "It was reported that the lncRNA NEAT1/miR-34c/NLRP3 axis regulates pyroptosis activation and that the lncRNA MEG3/miR-181a/Egr-1/TLR4 signaling pathway promotes fibrosis and the inflammatory response, both of which mediate the progression of diabetic nephropathy." (PMID 34941711, 2021). "In addition, MEG3 also plays a key regulatory role in kidney diseases such as ischemic reperfusion-induced AKI, diabetic nephropathy, and transplanted kidney injury." (PMID 34012408, 2021).
endothelial dysfunction (8 papers, 2017 to 2024). In vascular diseases, endothelial dysfunction is a systemic pathological state of the endothelium (the inner lining of blood vessels) and can be broadly defined as an imbalance between vasodilating and vasoconstricting substances produced by (or acting on) the endothelium. "Together, these reports indicate a plausible role of Meg3 in HFpEF by promoting fibrosis and endothelial dysfunction and point to its potential as a target for therapy in HFpEF." (PMID 38259314, 2023). "Apart from its role in fibrosis, Meg3 was also described to be involved in DM-induced endothelial dysfunction." (PMID 38259314, 2023). "Meg3 could promote Nlrp3-mediated inflammation in microglia, and its elevated expression could induce endothelial dysfunction." (PMID 39156629, 2024). "Elevated expression of lncRNA MEG3 induces endothelial dysfunction in HUVECs of IVF‐born offspring." (PMID 37470310, 2023). "lncRNAs such as ANRIL, MEG3, HOTAIR, and MALAT1 regulate vascular smooth muscle cell proliferation, endothelial dysfunction, and angiogenesis in COPD." (PMID 39201688, 2024). "In addition, MEG3 was positively correlated to hypertension in IVF offspring, together with lowered levels of eNOS and VEGF expression, inducing endothelial dysfunction." (PMID 38259314, 2023). "Notably, MEG3 is the only significantly increased lncRNA in senescent HUVEC, which suggests that MEG3 may mediate endothelial dysfunction in aging." (PMID 35047570, 2021).
laryngeal carcinoma (8 papers, 2019 to 2024). Carcinoma that arises from the laryngeal epithelium. "MEG3 was down‐regulated in laryngeal cancer tissues, and the low MEG3 expression was associated with advanced clinical stage." (PMID 31328388, 2019). "The findings indicated that the low MEG3 expression was associated with advanced clinical stage of laryngeal cancer patients." (PMID 31328388, 2019). "In laryngeal cancer cells, overexpressed MEG3 specifically binds and negatively regulates miR-23a, activates apoptotic protease activator factor-1 (APAF-1), and thus activates Caspase-9 and Caspase-3, leading to apoptosis." (PMID 36523500, 2022). "Further, another study pointed out that MEG3 regulated the expression of apoptotic peptidase activating factor 1 (APAF-1) by competitively binding to miR-23a in laryngeal cancer." (PMID 36544907, 2022). "LncRNA MEG3 blocks cell proliferation and induces cell apoptosis in laryngeal cancer through regulating miR-23a/APAF-1 axis." (PMID 32420340, 2020). "Overexpression of MEG3 inhibited the growth, proliferation and induced the apoptosis of laryngeal cancer cell in vitro and in vivo." (PMID 31328388, 2019). "MEG3 expression in 50 laryngeal cancer tissue samples was detected by reverse transcription‐quantitative polymerase chain reaction (RT‐qPCR)." (PMID 31328388, 2019). "In conclusion, the present study demonstrates that MEG3 acts as a novel tumour suppressive LncRNA in laryngeal cancer for the first time." (PMID 31328388, 2019). "In the present study, we found that overexpression of MEG3 inhibited the proliferation and induced the apoptosis in human laryngeal cancer cells and the similar evidence was also provided in vivo." (PMID 31328388, 2019). "Next, we explored the regulation of MEG3 on the apoptosis of laryngeal cancer cells using flow cytometry and Hoechst 33342 staining." (PMID 31328388, 2019). "The effects of MEG3 overexpression on laryngeal cancer cells were investigated in vitro and in vivo." (PMID 31328388, 2019). "In the present study, the result showed that the expression of MEG3 was down‐regulated in laryngeal cancer tissues." (PMID 31328388, 2019). "We further investigated the effect of MEG3 on the growth, proliferation and apoptosis of laryngeal cancer xenograft tumour in nude mice." (PMID 31328388, 2019). "In conclusion, the present study demonstrated that MEG3 functions as a novel tumour suppressive LncRNA in laryngeal cancer for the first time." (PMID 31328388, 2019). "Taken together, these results suggest that MEG3 inhibits the growth and proliferation and induces the apoptosis of laryngeal cancer cells in vivo." (PMID 31328388, 2019). "According to this result, we inferred that there existed reciprocal repression between miR‐23a and MEG3 in laryngeal cancer." (PMID 31328388, 2019). "Taken together, our results suggest that MEG3 inhibits the proliferation and induces the apoptosis of laryngeal cancer cells in vitro." (PMID 31328388, 2019). "The result showed that MEG3 expression was significantly down‐regulated in laryngeal cancer tissues compared with adjacent normal tissues." (PMID 31328388, 2019). "Undoubtedly, identifying the role and mechanism of MEG3 in laryngeal cancer will bring a novel insight into the progression of laryngeal cancer." (PMID 31328388, 2019). "Similarly, MEG3 inhibits laryngeal cancer cell proliferation and induces cell apoptosis by regulating APAF-1." (PMID 38281945, 2024). "The result of CCK‐8 assay showed that Hep‐2 and AMC‐HN‐8 cells transfected with MEG3 plasmid displayed a lower ratio of proliferation as compared with cells transfected with empty vector, which suggested that overexpression of MEG3 inhibited the proliferation of laryngeal cancer cells in vitro." (PMID 31328388, 2019). "Long non‐coding RNA (LncRNA) MEG3 serves a regulatory role in the progression of several types of cancer, but the role of MEG3 in laryngeal cancer is still unknown." (PMID 31328388, 2019).
laryngeal carcinoma (continued). "Thus, more studies should be conducted to confirm what extent the phenotype in laryngeal cancer induced by MEG3 was rescued by miR‐23a." (PMID 31328388, 2019). "The results showed that Hep‐2 and AMC‐HN‐8 cells transfected with MEG3 plasmid displayed a higher apoptosis rate as compared with cells transfected with empty vector, which suggesting that the apoptosis of laryngeal cancer cells was induced by up‐regulation of MEG3." (PMID 31328388, 2019). "The aim of this study was to explore the regulatory role and mechanism of MEG3 in laryngeal cancer." (PMID 31328388, 2019). "Additionally, MEG3 overexpression inhibited the proliferation and induced the apoptosis of laryngeal cancer cells in vitro and in vivo." (PMID 31328388, 2019). "In addition, MEG3 expression negatively correlated with miR‐23a level in laryngeal cancer samples." (PMID 31328388, 2019). "Taken together, these results support the conclusion that MEG3, miR‐23a and APAF‐1 form a ceRNA regulatory network in the progression of laryngeal cancer." (PMID 31328388, 2019). "Furthermore, MEG3 acts as a ceRNA to regulate APAF‐1 expression via competitively binding to miR‐23a, thereby regulating the progression of laryngeal cancer." (PMID 31328388, 2019). "Furthermore, MEG3 may act as a ceRNA to regulate APAF‐1 expression by competitive binding to miR‐23a, thereby regulating the progression of laryngeal cancer." (PMID 31328388, 2019). "First, although we have already demonstrated that the activations of APAF‐1 and its downstream caspases induced by MEG3 were rescued by miR‐23a, it is still not known whether the phenotype in laryngeal carcinoma induced by MEG3 was rescued by miR‐23a." (PMID 31328388, 2019).
nasopharyngeal carcinoma (8 papers, 2014 to 2025). A carcinoma arising from the nasopharyngeal epithelium. "Recent studies have indicated that HOTTIP and MEG3 are associated with the initiation and progression of various types of tumors, including nasopharyngeal carcinoma (NPC)." (PMID 39049088, 2024). "In silico analysis results explained why MEG3 polymorphisms could affect the sensitivity and toxicity of chemotherapy drugs in nasopharyngeal carcinoma patients." (PMID 34199840, 2021). "MEG3 copy number loss was found only in patients with nasopharyngeal carcinoma (NPC) whose LOI manifested as DMR hypermethylation." (PMID 38812777, 2024). "For instance, it was confirmed that nasopharyngeal cancer patients undergoing chemotherapy with the CC genotype of lncRNA MEG3 had a significantly higher (threefold) probability of severe anemia (grades 3–4) (OR = 3.00; p = 0.007)." (PMID 40150019, 2025). "Wang’s study showed that nasopharyngeal carcinoma patients with MEG3 rs10132552 CT genotype had a better response to treatment (OR = 0.261, p = 0.015)." (PMID 31488093, 2019). "Downregulation of MEG3 also promoted sequestosome 1 (SQSTM1) expression in nasopharyngeal carcinoma cells and is responsible for the increased migration, invasion and EMT in NPC cells." (PMID 40176927, 2024).
osteoporosis (8 papers, 2018 to 2024). A condition of reduced bone mass, with decreased cortical thickness and a decrease in the number and size of the trabeculae of cancellous bone (but normal chemical composition), resulting in increased fracture incidence. "Based on previous studies, several ubiquitous lncRNAs, including Malat1, H19, Hotair, MEG3 and Dancr, were previously reported to be associated with osteoporosis." (PMID 36983039, 2023). "Bone disorders like osteoporosis and bone cancers are associated with MEG3 dysregulation." (PMID 39156986, 2024). "The review also revealed that dysregulation of MEG3 is prevalent in a variety of bone diseases such as osteoporosis, osteoarthritis, and bone cancer." (PMID 39156986, 2024). "The study demonstrates that the expressions of MEG3 in MSCs from postmenopausal women with osteoporosis (PMOP) and ovariectomized (OVX) mice are significantly higher than that of their healthy controls, respectively." (PMID 36778210, 2023). "lncRNA MEG3 inhibits osteogenic differentiation through down-regulating miR-133a–3p and its expression is increased in bone marrow stem cell of ovariectomized mice and osteoporosis patients." (PMID 35308164, 2021). "By specifically targeting MEG3, the therapeutic potential is presented for the restoration of normal bone metabolism, the modulation of bone-related signaling pathways, and the development of novel treatments for a variety of bone illnesses, such as osteoporosis and bone cancer." (PMID 39156986, 2024). "Several lncRNAs, including Malat1, H19, HOTAIR, MEG3 and DANCR, were largely involved in the osteoporosis." (PMID 36983039, 2023). "It was only recently that DEPTOR was found to play a novel function in osteogenic differentiation by inhibiting MEG3-mediated activation of BMP4 signaling, suggesting its involvement in osteoporosis." (PMID 32390946, 2020). "The lncRNA MEG3 (maternally expressed 3) was found to promote osteoporosis in non-cancerous subjects." (PMID 32664424, 2020).